HOXB13 (homeobox B13)
Diseases named in the same sentence as HOXB13 in open-access papers (continued):
Sharing a sentence is not in itself a finding about the gene and the disease.
infection (1 paper, 2019). The state of being infected such as from the introduction of a foreign agent such as serum, vaccine, antigenic substance or organism. "To elaborate on the relationship between DNMT3B and HOXB13, we used lentiviral infection to knock down or overexpress DNMT3B in the HCT116 and RKO cell lines, and the efficiency of DNMT3B knockdown and overexpression was assessed by western blotting." (PMID 31815008, 2019). "To address the biological function of HOXB13, we used lentiviral infection to knock down or overexpress HOXB13 in CRC cell lines." (PMID 31815008, 2019).
kidney disease (1 paper, 2023). "The HOXB13 −/TFF3+ subgroup exhibited higher preoperative serum creatinine levels and kidney disease stages than the HOXB13−/TFF3− subgroup, implying a role for TFF3 in kidney function." (PMID 37894380, 2023).
HOXB13 also shares sentences with these, for which no sentence is quoted: Lynch syndrome (3 papers); non-melanoma skin carcinoma (3); skin cancer (3); invasive breast carcinoma (2); non-small cell lung carcinoma (2); stomach cancer (2); acute myeloid leukaemia (1); basal cell carcinoma (1); benign prostatic hyperplasia (1); breast/ovarian cancer (1); chronic lymphocytic leukaemia (1); colon (1); diffuse midline glioma (1); endothelial dysfunction (1); Fanconi anemia (1); fibrolamellar carcinoma (1); glioma (1); glioneuronal tumor (1); heart disease (1); hereditary cancer syndrome (1); hereditary colorectal cancer (1); invasive carcinoma (1); lymph node- (1); meningioma (1); multiple myeloma (1); myeloid leukemia (1); neuroendocrine carcinoma (1); non-Hodgkin lymphoma (1); oral squamous cell carcinoma (1); paraganglioma (1).
A further 8 diseases each share a sentence with HOXB13 in 1 paper.